FBXW7 (F-box and WD repeat domain containing 7)
Diseases named in the same sentence as FBXW7 in open-access papers (continued):
Sharing a sentence is not in itself a finding about the gene and the disease.
tumor (continued). "Additionally, circular RNA circPSD3 sponges MiR-25-3p, thereby restoring FBXW7 expression and inhibiting epithelial-mesenchymal transition (EMT) and tumor metastasis." (PMID 39749199, 2024). "In B-lymphoma cells, the mutation or knockdown of KMT2D inhibited methylation of lysine 4 on histone H3 (H3K4), downregulated FBXW7 expression, activated NOTCH signaling pathway and downstream MYC/TGF-β1, resulting in alterations of tumor-induced regulatory T cell trafficking." (PMID 39113693, 2024). "Considering the inhibition of FAM83D on FBXW7 expression and the well-recognized tumor suppressive roles of FBXW7 in multiple cancers, we then investigated whether FAM83D-induced malignant phenotypes of BC cells was mediated by FBXW7 down-regulation." (PMID 38454442, 2024). "Parallel to this, EZH2 inhibits FBXW7 and NUMB production by trimethylating histone H3 at Lys27 (H3K27me3), which activates anti-apoptotic genes and expresses T-cell multifunctional cytokines that attenuate immunosuppression in late tumor stages." (PMID 37658431, 2023). "FBXW7 has been shown to interact with cyclin E, exploring the potential link between FBXW7 and the cyclin/CDK pathway would be useful in elucidating the mechanism of breast carcinogenesis." (PMID 37658431, 2023). "FBW7 (F-box and WD Repeat Domain-containing 7), a component of the ubiquitylation pathway(s), is a tumor suppressor for multiple human cancers and a negative regulator of steady-state levels of KLF13." (PMID 38067370, 2023). "While other of them are lowly expressed in tumor tissues, which can continuously activate their host genes and inhibit the malignant phenotype of tumors as tumor suppressors, such as circ-Foxo3, circ-ITCH and circ-FBXW7." (PMID 37060016, 2023). "FBXW7 acts as a tumor suppressor by promoting the ubiquitination and degradation of various substrates including c-Myc, c-Jun, cyclin E, and MCL-1, which usually function as oncoproteins and promote tumor growth and survival." (PMID 37006236, 2023). "From above, we could speculate that FBXW7-mediated ferroptosis modification may promote the activation of TME DCs, thus enhancing the intratumoral anti-tumor immune response." (PMID 35818395, 2022). "Therefore, through our work, we uncover the mechanism by which FBXO9 exerts a tumor-promoting effect in HCC and propose a novel FBXO9-involved degradation mechanism of FBXW7." (PMID 35847937, 2022). "Moreover, non-coding RNAs regulate tumor properties of invasion and metastasis via EMT in part through interacting with FBXW7." (PMID 35515121, 2022). "In a previous study, we applied a tissue microarray and IHC in 102 pairs of tumor and adjacent noncancerous tissues and revealed that FBXW7 has remarkably lower expression in tumor samples." (PMID 36159747, 2022). "Similar to the previous reporting the driver genes in CC, FBXW7, EP300, CASP8 and FAT1(10%, 20%, 10% and 10% of tumor, respectively) were also identified in our cohort with a low frequency, which may result from a small sample size in our cohort." (PMID 34221990, 2021). "Taken together, these data suggest that FBXW7 (and perhaps other SCF complex members) may exhibit tumor suppressor and/or oncogene-like functions in a context/tissue-dependent manner." (PMID 35008511, 2021). "On the other hand, in vivo studies have suggested that the downregulation of miR-92a suppresses the biological processes of tumor growth in HCC and that F-box and WD repeat domain-containing 7 (PBXW7) is a direct target of miR-92a, promoting tumor progression in this setting." (PMID 32793278, 2020).
tumor (continued). "FBXW7, as a WD40 repeat‐containing protein, targets numerous oncoproteins, including mammalian target of rapamycin, c‐myc, cyclin E, c‐Jun and steroid receptor coactivator‐3 for ubiquitination‐mediated degradation and inhibition of tumour growth." (PMID 32394588, 2020). "MiR-92a has been shown to promote tumor growth of HCC by targeting F-box and WD repeat domain-containing 7 (FBXW7) and may serve as a novel prognostic biomarker and therapeutic target." (PMID 31640265, 2019). "The identification and characterization of these non-degradative substrates largely extends the mechanism of FBXW7 action as a tumor suppressor." (PMID 31342282, 2019). "Although there are no published reports that FBXW7 mutated in the CRC stroma, research shows that stromal mutations can promote tumours in genetically at-risk tissue in other systems." (PMID 30783098, 2019). "In addition, radiation-induced tumor latency is shorter in FBXW7 heterozygous and PTEN heterozygous knock-out mice (FBXW7+/−; PTEN+/−) compared to FBXW7 heterozygous knock-out mice (FBXW7+/−) and PTEN heterozygous knock-out mice (PTEN+/−)." (PMID 30086763, 2018). "It is not unusual that genes with apparent in vivo tumour suppressor or oncogenic capacity have relatively small or moderate effect in in vitro assays including a F-box family protein, FBXW7, for its role in cell migration and invasion." (PMID 28698647, 2017). "Further research is needed to clarify the role of FBXW7 in the UPR and tumor development." (PMID 26575021, 2015). "IHC staining confirmed the downregulation of FBXW7 in cancer tissues compared with tumor adjacent nontumorous tissues in IHCC and PHCC, but not in DCC." (PMID 25749036, 2015). "Furthermore, Fbxw7 expression was significantly correlated with tumor size, venous infiltration, Edmondson–Steiner grading and TNM tumor stage, which is consistent with our previous study." (PMID 24884509, 2014). "Furthermore, 20 cases were subjected to immunoblotting for Fbxw7; we found that the Fbxw7 protein level in HCC tissues was significantly lower than that in the matched normal, tumor adjacent, tissues (P < 0.01)." (PMID 24884509, 2014). "Our results suggest that Fbxw7 may target YAP for ubiquitination and proteasomal degradation, thereby inhibiting HCC growth and hence tumor progression." (PMID 24884509, 2014). "Among them, FBXW7 targets mTOR for degradation and cooperates with PTEN in tumor suppression." (PMID 22292069, 2012). "In addition, PRR11 expression was significantly positively correlated with tumor stage and pathological grade, and although FBXW7 expression did not significantly differ with tumor stage or tumor size, it exhibited a negative correlation trend." (PMID 40083925, 2025). "Notably, FBXW7 controls the expression of multiple oncoproteins, including Cyclin E1, transcriptional factors c-Myc and c-Jun, Notch receptor, SREBP (a coactivators of PARPγ) and transcriptional factor PGC-1α, thereby suppressing tumor development." (PMID 41373479, 2025). "However, lower effect magnitudes were not universal as inactivation of Rnf43 or Fbxw7 increased tumor growth as much or more in Braf;Cas9 mice than in G12C;Cas9 mice." (PMID 37828026, 2023). "In addition, PIN1 may execute the oncogenic role through promoting the degradation or inactivation of tumor suppressors such as PML and FBXW7." (PMID 36813923, 2023). "The main evidence emerging from this study is that IPA and its analog N6-BA could influence the expression of methylated genes involved in tumor-related mechanisms, such as MGMT, FBXW7, and potentially others, suggesting the existence of an epigenetic regulation behind their pleiotropic actions." (PMID 35559231, 2022).
tumor (continued). "To validate whether FBXW7 contributes to the anti-tumor phenotype regulated by METTL3, we generated stable cells expressing the indicated genes to determine whether FBXW7 overexpression could rescue the effects of METTL3 knockdown on the biological behavior of HCC827 or PC9 cells." (PMID 33676554, 2021). "Taken together, these data clearly demonstrate the crucial importance of FBXW7 tumor suppressor activity in SCCs development and support the notion that FBXW7 mutation might be exploited as a predictive marker to guide novel therapeutic treatments." (PMID 32560247, 2020). "For instance, F‐box protein FBXW7 functions as a tumor suppressor by promoting proteasomal degradation of c‐Myc, Cyclin E, and Notch, whereas SKP2 functions as an oncogene by promoting degradation of tumor suppressors and activating AKT signaling by abrogating its proteasomal degradation." (PMID 30714168, 2019). "Furthermore, in vitro and in vivo overexpression of FBXW7 in GC was found to markedly induce apoptosis and inhibited EMT by binding and degrading Ras homologue gene family, member A (RhoA), thereby manifesting its tumor suppressive action in GC." (PMID 30791487, 2019). "Similarly, si circ-FBXW7 stimulated the tumor growth and circ-FBXW7 overexpression repressed the tumor progression in SW480 and SW620 tumor models, which suggested that circ-FBXW7 could serve as a target biomarker of CRC." (PMID 31519156, 2019). "Nevertheless, the function of FBXW7 in tumor metastasis is not commonly reported." (PMID 29097832, 2017). "FBXW7 promotes ubiquitination of XRCC4 via lysine 63 linkage to facilitate nonhomologous end-joining, rather than proceeds to XRCC4 degradation, while these two pathways of ubiquitination (via K48 and K63 linkage) contribute to the tumor suppressor role of FBXW7 together." (PMID 28422719, 2017). "However, unlike many TS genes, FBXW7 does not follow a classic model of tumor suppression, as monoallelic alterations appear to be sufficient for cancer development." (PMID 26482194, 2015). "Interestingly, restoring YAP can partially abolish the effect of Fbxw7 on anti-HCC, suggesting that Fbxw7 may exert its tumor suppressive function by regulating the stability of the YAP protein." (PMID 24884509, 2014). "Together, these findings show that FBXW7 physically interacts with CHD4 and mediates its ubiquitination, which highlights that targeting CHD4 may be a promising therapeutic strategy for eradicating BCSCs to overcome tumor relapse, metastasis and drug resistance in TNBC." (PMID 38268032, 2024). "Results indicated that all OSCC cell lines expressed lower levels of FBXW7 than HOK cells, indicating its negative role in tumor progression." (PMID 32792479, 2020). "Immunohistochemical analysis showed that FBXW7, STK40, and PDCD4 protein was moderately/strongly expressed in the basal/suprabasal cells of ZST esophagus, but reduced or absent in hyperplastic/tumor-bearing ZD3T, ZD6T, and ZD12T esophagus." (PMID 26918602, 2016). "IMR90 cells, on the other hand, seemed to be impacted by a different panel of genes, BTG2, FBXW7, NDUFAF2, PHLDA1, and DMD, whose knockdown did not have a significant impact in the two tumor cell lines, suggesting cell line-specific effects." (PMID 24009623, 2013).
tumor (continued). "Furthermore, the mRNA expression of FBXW7 was decreased and that of WDR5 was increased in BDNF-AS-overexpressing tumor tissues, but VDAC3 expression was not significantly changed." (PMID 35280682, 2022). "Taken together, FBXW7 may influence the survival outcomes of CRC patients through regulating local invasion and lymph node metastasis but not tumor growth." (PMID 34217244, 2021). "FBXW7 can inhibit CCL2 gene transcriptional activation by negatively regulating NOTCH expression levels; and inhibition of CCL2/CCR2 signaling has been shown to suppress tumor metastasis demonstrating an important role of the FBXW7/NOTCH/CCL2 axis in the regulation of cancer metastasis." (PMID 35346215, 2022).
cancer (451 papers, 2007 to 2026). A tumor composed of atypical neoplastic, often pleomorphic cells that invade other tissues. "It has been confirmed that FBXW7 gene mutations or downregulations have been found in many types of malignant tumors, which facilitate the uncontrolled proliferation, enhanced invasion and migration, and drug resistance of cancer cells." (PMID 40809696, 2025). "Whilst there are numerous studies highlighting that FBXW7 mutations are enriched in HPV+ cancers, investigating the substrates and effects of these mutations are needed to provide a better understanding of their function." (PMID 40011575, 2025). "The FBXW7 gene plays a complex role in tumorigenesis: both its overexpression and its inactivating mutations have been implicated in cancer development, and numerous preclinical studies have investigated its function in this context." (PMID 41373479, 2025). "SP2509 has been relatively well-studied, particularly in a study that found LSD1 to be upregulated in PC and associated with prognosis, promoting cancer cell survival by downregulating FBXW7 protein levels." (PMID 41496857, 2025). "Loss of FBXW7 sensitizes cancer cells to some drugs, while developing resistance to other types of chemotherapies." (PMID 41373479, 2025). "According to COSMIC data, FBXW7 mutations occur in approximately 7.8% of all human cancers, with the highest prevalence in cholangiocarcinoma (35%), T-cell acute lymphoblastic leukemia (31%), endometrial (9%), and gastric cancers (6%)." (PMID 41373479, 2025). "The use of mTOR inhibitors can mitigate EMT characteristics and cancer stem cell properties induced by FBXW7 mutations." (PMID 39749199, 2024). "The loss of FBXW7 is strongly associated with the maintenance of cancer cell stemness because it contributes to the protein degradation of cancer stemness markers, such as c-Myc and Nanog." (PMID 38892210, 2024). "The present study aimed to investigate the KCa1.1 inhibition-mediated regulation of FBXW7 expression and its associated signaling cascades, including CEBPs and miRNAs, in KCa1.1-expressing cancer cells." (PMID 38892210, 2024). "The loss of the E3 ubiquitin ligase, FBXW7 synergizes with the acquisition of stemness and anti-cancer resistance and the accumulation of pluripotent transcription factors, such as c-Myc in cancer cells." (PMID 38892210, 2024). "Consistent with this notion, genomic deletion or mutation of FBXW7 has frequently been reported in various cancers, with a cancer-wide average frequency of 6%." (PMID 38268032, 2024). "One of the markers for cancer stemness, c-Myc is a well-known major target for protein degradation by FBXW7, and the down-regulated expression of FBXW7 is associated with the accumulation of c-Myc proteins in cancer cells." (PMID 38892210, 2024). "Some of them, such as FBXW7, are mutated or show high-frequency expression deregulation in a large number of human malignant tumors, suggesting a key role in cancer development or progression." (PMID 38903918, 2024). "Accordingly, FBXW7 depleted cells are resistant to death and many studies have linked it to a range of cancers." (PMID 37183425, 2023). "Alterations in FBXW7 expression have been linked to the development and progression of several types of cancer." (PMID 37047300, 2023). "We review new findings that provide insights into the consequences of “hotspot” missense mutations of FBXW7 that are found in human cancers." (PMID 37681873, 2023). "We conclude that FBXW7-mutant cells from multiple cancer types are more sensitive to ATR inhibition, which is broadly applicable to several cancer types, revealing a druggable synthetic lethal interaction between DNA repair genes and FBXW7 mutations." (PMID 38032106, 2023). "Fbxw7 mainly serves as a cancer suppressor, and mutation or Loss of Fbxw7 is frequently found in multiple human tumors including GBM." (PMID 36971192, 2023).